Y_RNA (Y RNA )
Gene: Miscellaneous RNA gene on chromosome 2 (39,128,826 to 39,128,927, reverse strand). Ensembl gene ENSG00000202309.
Homologues: Orthologues: chimpanzee Y_RNA (99% identical), macaque Y_RNA (97% identical). Paralogues in human: Y_RNA (93% identical), Y_RNA (92% identical), RNY3 (91% identical), Y_RNA (91% identical), RNY3P1 (90% identical), Y_RNA (90% identical), Y_RNA (89% identical), Y_RNA (88% identical), Y_RNA (87% identical), RNY3P14 (86% identical), Y_RNA (86% identical), RNY3P11 (85% identical), and 99 more.